CDK4 (cyclin dependent kinase 4)
Diseases named in the same sentence as CDK4 in open-access papers (continued):
Sharing a sentence is not in itself a finding about the gene and the disease.
cancer (continued). "Most driver mutations in cancer occur in mitogenic signaling pathways, implying that cancer cells may express high levels of c-Myc and more likely adapt to CDK4/6 inhibition than non-transformed cells." (PMID 38030655, 2023). "Such responses across cell types may also impact therapeutic strategies targeting CC (e.g., CDK4/6 inhibitors), for example in cancer, and understanding the interplay between CC and immune activation may represent a promising avenue for therapeutic investigation." (PMID 36521490, 2023). "In addition to their classical role in inhibiting the cell cycle progression and proliferation of cancer cells, CDK4/6 inhibitors also activate the immune system by stimulating the upregulation of MHC I on the membrane of cancer cells and producing interferon (IFN) in RB‐dependent mechanism." (PMID 36457244, 2023). "However, resistance to CDK4/6i leads to treatment failure and cancer progression." (PMID 38293701, 2023). "Similarly, CDK4/6 inhibition may increase PD-L1 levels in cancer cells, making them substantially more sensitive to PD-1 blocking therapy." (PMID 35682571, 2022). "Therefore, CDK4/6 inhibitors are a promising new cancer therapy." (PMID 36065138, 2022). "Indeed, this is the main mechanism of small molecule inhibitors of CDK4/6 in cancer treatment." (PMID 34687270, 2022). "However, even though cancer cells are arrested after CDK4/6 inhibitor treatment, genes regulating senescence in this context are still unknown limiting their antitumour activity." (PMID 35184131, 2022). "Thus, selective inhibition of CDK4/6 is a promising cancer treatment." (PMID 35621970, 2022). "Therefore, CDK4/6i have emerged as an attractive therapeutic strategy for cancer treatment." (PMID 35270034, 2022). "Therefore, CDK4/6 are appealing targets for novel cancer therapeutics." (PMID 35164144, 2022). "In addition to impacting the cancer cell, CDK4/6 inhibitors also impact the immune response." (PMID 35911672, 2022). "Therefore deciphering the association between CDK4 and RBBP7 may provide a promising method for cancer treatment." (PMID 35538026, 2022). "The interaction of CDK4 and CDK6 with D-type cyclins constitutively phosphorylates and inactivates the retinoblastoma protein (Rb), a tumor suppressor, causing the release of its binding partner, E2 transcription factor (E2F), allowing cancer cells to overcome pRb-dependent growth suppression." (PMID 35459184, 2022). "Additionally, inhibition of CDK4/6 may impair the recovery of damaged and micronucleated cancer cells from prior exposure to paclitaxel, further enhancing the efficacy." (PMID 36185294, 2022). "Although our data fully support the reported binding of Id2 to hypo-phosphorylated Rb, we hypothesize that in anchorage-independent carcinoma cells, formation of the Id2-Rb complex prevents CDK4/6-dependent Rb phosphorylation by retaining or accumulating Rb in its hypo-phosphorylated active form." (PMID 35437308, 2022). "This indicates that CDK4 could be a target for the treatment of malignant tumors." (PMID 33968776, 2021). "However, CDK4/6 inhibitors could reverse the multi-aggressive phenotypes of SCP3 in immune-refractory cancer and lead to a long-term response to ICIs." (PMID 34026622, 2021). "However, previous studies have shown that the use of single-agent therapies with CDK4/6i offer only modest improvements in most cancer types, therefore clinical trials are testing CDK4/6i combined with chemotherapy across a number of malignancies, including PC." (PMID 34828525, 2021). "In this study we evaluated a number of cancer variants that are associated with resistance to endocrine therapy alone or in combination with or without PI3K/AKT/mTOR or CDK4/6 inhibitors, such as PTEN gene copy number loss and ESR1 activating mutations and copy number gain." (PMID 34471951, 2021).
cancer (continued). "Since CDK4/6i block both normal and cancer cells in the G0/G1 phase of the cell cycle, it was firstly hypothesized that the use of these novel agents in combination with standard chemotherapies could be detrimental for the efficacy of the cancer treatment." (PMID 34204543, 2021). "In addition, selective CDK4/6 inhibition allows preferential inhibition of oncogenic events while sparing toxicity in normal tissues and therefore represents an appealing therapeutic strategy for cancer." (PMID 33845905, 2021). "More recently, transcriptome analyses performed in different cancer cell models modified for CDK4 and CDK6 expression or activity, highlighted that, beyond the control of the G1 phase of the cell cycle, CDK4 and CDK6 might play non-cell cycle related functions via the regulation of transcription." (PMID 34204543, 2021). "Therefore, better knowledge of how patient metabolism and DDIs could affect both the efficacy and safety of CDK4/6 inhibitors should always be considered to maximize the personalization of cancer care in patients with ABC." (PMID 33477469, 2021). "However, as a CDK2/4/6 triple inhibitor, vanoxerine dihydrochloride may have broader activity and will be effective to a larger number of cancers than CDK2 or CDK4/6 inhibitors." (PMID 33579185, 2021). "The recent observation that CDK4/6 inhibitors, now widely employed to treat luminal-like BCs, not only restrain cancer cell proliferation but also favor antitumor immunity by inhibiting CD4+ Treg proliferation in preclinical models, may be important in this regard." (PMID 34552178, 2021). "Dysregulation of CDK4 could lead to multiple pathological processes, diseases or even cancer." (PMID 33452764, 2021). "Furthermore, many human cancers harbor genomic or transcriptional aberrations that could activate CDK4/6." (PMID 34641869, 2021). "Therefore, CDK1 and CDK4 were found to be potential cancer therapeutic targets." (PMID 34290286, 2021). "Since RB1 function can clearly be compromised by multiple events in addition to direct genetic loss in human cancers (e.g., HPV-E7 or CDK4/6 activity), we focused on developing a transcriptional tool to evaluate RB activity based on transcription that could be broadly deployed across tumors." (PMID 32242058, 2020). "Other possible advantages of SKP2 as a therapeutic target in cancer include the potential for selective targeting compared with the use of other signaling inhibitors with broader activities or higher toxicity, such as the proteasomal inhibitor bortezomib or the CDK4/6 inhibitors." (PMID 31772299, 2020). "Further work is necessary to determine whether PIM inhibition contributes to the diverging activity of the two drugs in these, or other, contexts and, more generally, to investigate the cancer types and context where combined CDK4/6 and PIM inhibition may be advantageous." (PMID 32391118, 2020). "Thus, cdk4, cdk6, e2f1, and rb1 not only participate in the progression of cancer cells but might also be useful biomarkers for predicting prognosis in some tumors." (PMID 32357912, 2020). "Considering that beyond the inhibition of cell proliferation, the CDK4/6 inhibitors may exert other effects on cancer cells such as the induction of a senescent-like phenotype, we tested the production of the Senescent-Associated β-galactosidase enzyme (SA-β-Gal) in these resistant cell models." (PMID 33374971, 2020). "Moreover, aberrant CDK4/6-RB1 signaling has been reported in a range of cancers." (PMID 33282875, 2020). "Considering that the large fraction of patients with RB-deficient cancers may not benefit from CDK4/6i, we then determined whether the combined inhibition of CDK4/6 and PARP showed synergistic effect in RB-deficient cancer cells." (PMID 32249776, 2020). "Finally, we expect this communication between the BCL2 family and the CDK4/6-RB pathway to exist beyond the realm of cancer and may have significant impact in normal cellular proliferation, stem cell growth, and differentiation." (PMID 32111816, 2020).
cancer (continued). "NR2F2-AS1 by regulating CDK4 could promote cancer cell proliferation in Pca." (PMID 33330110, 2020). "Thus inhibiting expression of CDK4/6 proteins may be more effective than simply suppressing its activity in treatment of cancer." (PMID 32792963, 2020). "We then evaluated if there was any alteration in some of the principal effectors of this axis commonly deregulated in cancer (RB, E2F, CDKN2A, CCDN1, CDK4) by amplification, deletion, or mutation that could be associated with the expression pattern of the lncRNA22." (PMID 31934613, 2020). "Since the dysregulation of the cell cycle is one of the crucial characteristics of malignant tumors, we aimed to investigate whether CDK4/6 inhibitors can be applied to various tumors and whether they can be as effective as traditional chemotherapy drugs in most tumors." (PMID 32357912, 2020). "In addition, suppression of cyclin D and CDK4 leads to growth arrest in carcinoma cells." (PMID 32118302, 2020). "Herein, CDK4 which regulates the G1-S phase cell cycle transition could bind to cyclin D1 (D-type cyclin) for deactivating tumor suppressor retinoblastoma protein (Rb) in cancer cells." (PMID 30808351, 2019). "Importantly, CDK4/6 activity is commonly elevated in cancer cells." (PMID 30959874, 2019). "However, it is not known whether P16 inactivation by DNA methylation may similarly increase the sensitivity of cancer cells to these CDK4/6 inhibitors." (PMID 31652270, 2019). "Hence, we sought to determine whether cancer cells with P16 methylation exhibit increased sensitivity to therapeutic CDK4/6 inhibitors." (PMID 31652270, 2019). "Therefore, hypophosphorylation of retinoblastoma family members by the application of CDK4/6 inhibitors may suppress PARP1 transcription in fast growing cancer cells." (PMID 29306194, 2018). "In addition, CDK4/6 has a pivotal role in the G1–S-phase cell cycle transition in cancer." (PMID 29502166, 2018). "In addition, CDK4/6 inhibitors have recently been developed to reactivate the RB-pathway in cancer." (PMID 28293272, 2017). "Thus, overexpression of CDK4 and cyclin D1 is invariably correlated with cancer progression." (PMID 29183322, 2017). "However, not all cancer cells respond to CDK4/6 inhibition, and loss of RB1 renders cells insensitive." (PMID 29222471, 2017). "Therefore, we tested whether the inhibition of the CDK4-RB axis by fascaplysin is a major mechanism for its anti-cancer effect." (PMID 28961193, 2017). "However, we could not rule out the possibility that serum TK1 activity is reduced only in CDK4/6-dependent cancer cells." (PMID 29162134, 2017). "Thus, CDK4/6 activity appears as a promising therapeutic target for cancer treatment." (PMID 27323399, 2016). "Thus, the investigation of the molecular mechanism by which PF down-regulates cyclin D1 and CDK4 expression may be required to understand how to better treat cancer and even to develop better anti-cancer drugs." (PMID 27670681, 2016). "Thus, CDK4/6 activity appears to represent a promising therapeutic target for cancer treatment." (PMID 26528855, 2015). "Interestingly, a previous study in a cancer cell line has shown that CDK4/6 could control the transcriptional activity of Smad2/3." (PMID 24074866, 2013). "A requirement for the FPPRGPRPVQSV region of Cdk4 to provide energy for cancer cell division could also provide an explanation for the fact that Cdk4 rather than Cdk2 or Cdk6 appears to be the mandatory cyclin-dependent kinase for carcinogenic malignant transformation." (PMID 21668989, 2011).
cancer (continued). "PRGPRP at high concentration may cause selective cancer cell necrosis by inhibition of anaerobic ATP provision, either as an isolated activity of presently unknown mechanism, or by competitive inhibition of the FPPRGPRPVQSV region of Cdk4." (PMID 21668989, 2011). "However, no study has up to date investigated the CDK4 variant in the human genome of cancer patients to prove their potential role in oncogenic pathogenesis." (PMID 19327170, 2009). "Could the combined targeting of Cdk2 and Cdk4 be a valuable approach for cancer therapy?" (PMID 16759374, 2006). "Palbociclib (CKI) is a selective inhibitor of cyclin-dependent kinases CDK4 and CDK6, which blocks cell cycle progression at the G1/S transition and effectively suppresses cancer cell proliferation." (PMID 41362743, 2026). "Treatment with CDK4/6 inhibitor Abemaciclib sensitizes HR+ and TNBC cancer cells to lysosomotropic agent-induced cell death." (PMID 39930269, 2025). "Tumors that overexpress MYC often exhibit heightened sensitivity to CDK4/6 inhibition, making this axis a selective vulnerability in MYC-driven cancers." (PMID 40076599, 2025). "Studies have found that CDK4 and CDK6 are frequently overexpressed in pediatric B-ALL patients, with cancer cells relying on this pathway for excessive proliferation." (PMID 41155287, 2025). "Another important finding of our study were the differences in mitochondrial dynamics and function in CDK4-KO cells, which add another layer of complexity to the understanding of the role of CDK4 in TNBC and possibly in other cancers." (PMID 39788939, 2025). "Because they are important in regulating the cell cycle, CDK1, CDK2, CDK4, and CDK6 have been proposed as potential targets for cancer treatment." (PMID 38231074, 2025). "In two clinical trials where CDK4/6is plus ET were given in the neoadjuvant setting, IRPS and other IFN-related signatures were overexpressed in a cancer population that was intrinsically insensitive to CDK4/6is." (PMID 40244377, 2025). "Palbociclib, a selective CDK4/6 inhibitor, has shown potential in treating HPV− HNSCC by inducing G1 phase cell cycle arrest and reducing cancer cell viability." (PMID 40940964, 2025). "For cancer lineages predicted to retain BCL-xL addiction after TIS, a senogenic pulse (e.g., a CDK4/6 inhibitor, a PARP inhibitor, or ionizing radiation) can be administered." (PMID 41280927, 2025). "Given the structural and functional similarities between CDK4 and CDK6, which facilitate functional compensation, studying these enzymes together is crucial for enhancing our understanding of cancer treatment strategies." (PMID 40223929, 2025). "Targeting CDK6 in cancer represents an attractive therapeutic option as CDK6 activity is frequently enhanced in disease and CDK4/6 kinase inhibitors are available for clinical use." (PMID 39966356, 2025). "The greatest success has come from inhibiting cell cycle CDKs, especially CDK4 and CDK6, in certain cancer types." (PMID 39800748, 2025). "Genes encoding proteins such as cyclin-dependent kinase 2 (CDK2), cyclin-dependent kinase 4 (CDK4), CDC28 protein kinase 1B (CKS1B), cyclin A2 (CCNA2), and cyclin D1 (CCND1) play key roles in promoting cell division and cancer progression." (PMID 41003013, 2025). "CDK4/6 inhibitors control E2F activity by abolishing CDK-mediated Rb phosphorylation and are thus effective in the treatment of cancer with intact canonical Rb-E2F pathway." (PMID 40519166, 2025).
cancer (continued). "For each of the three paired cancer cell lines, we used gene expression and protein phosphorylation assays to test whether compensatory GF signal-mediated proliferation phenotypes (predicted from scRNAseq analyses of patient tumors) emerged in vitro under endocrine and CDK4/6i treatment." (PMID 40341770, 2025). "When comparing HLA-E positive with HLA-E negative cancer cells, analysis of the top 50 DEGs revealed several cell cycle-related genes that were highly expressed in HLA-E positive cancer cells, including CDKN1A, CDK4, and MDM2." (PMID 40959273, 2025). "By analyzing interactions with the GNPDA1 protein using the STRING database, researchers identified 4 key genes (GABPB1, CDK4, ADNP, and APH1A) that play important roles in cellular processes related to cancer." (PMID 40419932, 2025). "The present study investigated the potential of AU2–94, a first-in-class CDK4 inhibitor, to protect BM cells during myelosuppressive chemotherapy in TNBC, beyond its established application in RB-positive cancers." (PMID 40478388, 2025). "The approval of CDK4/6 inhibitors has spurred interest in next-generation of CDK2 inhibitors, which show potential in cancer therapy." (PMID 39800748, 2025). "Conversely, IAP-based PROTACs degraded both CDK4/6 and IAP proteins, resulting in synergistic effects on cancer cell growth." (PMID 40793752, 2025). "Our findings bridge the gap between the structural similarity and functional divergence of CDK4 and CDK6, advancing the understanding of kinase regulation in cancer biology." (PMID 40093074, 2025). "This investigation demonstrated that kaempferol affects cancer cells by downregulating CDK1, CDK4, CDK6, and CDK7 at both the gene and protein levels in MDA-MB-231 cells, and specifically CDK6 and CDK7 in MDA-MB-468 cells." (PMID 41463161, 2025). "For example, the potential to restore immunotherapeutic sensitivity to STK11-driven cancers by inhibiting CoREST deacetylase activity has been explored via Tango Therapeutics’ compound TNG26060, or via inhibitors of AXL, CDK4/6, or STAT361–63." (PMID 40791513, 2025). "Experimental results indicate that high doses of DEH can also suppress the expression of CDK4, CDK6, and p21, regulating the cell cycle, inducing cell cycle arrest in cancer cells, and promoting apoptosis in cancer cells." (PMID 40468178, 2025). "Resistant cancer cells have increased MAPK activation, leading to CDK4/6-RB bypass and disease progression." (PMID 40075623, 2025). "CDK4 and CDK6 are key proteins of cellular entry into the S phase, which is critical for the onset and progression of many cancers." (PMID 40138292, 2025). "The CDK4-MYC axis is not limited to cell cycle regulation; it also plays a key role in the metabolic reprogramming of cancer cells." (PMID 40076599, 2025). "These medications target CDK4 and CDK6 proteins on cancer cells, inhibiting cellular proliferation and blocking the progression from G1 to S phase in the cell cycle." (PMID 40136358, 2025). "CDK4 and CDK6 are of specific relevance in cancer and promote the transition from G1 to S cell cycle phases through the phosphorylation of retinoblastoma protein (Rb)." (PMID 40094009, 2025). "It was reported that prolonged CDK2 inhibition increased cancer cell reliance on the CDK1 pathway, while rapid adaptation depended on expression of the CDK4/6 pathway." (PMID 40232858, 2025). "In cancer cells, CDK6 overexpression often outcompetes CDK4 in driving cell cycle progression, contributing to resistance against CDK4/6 inhibitors (CDK4/6i)." (PMID 40093074, 2025). "Taken together, miR-34a is an important regulator of leukemogenesis through different mechanisms including inhibition of CDK4, MYB, and SIRT1 expression, and/or suppression of B-Myb and E2F1 expression, leading to cell cycle arrest in cancer cells." (PMID 38361758, 2024).